TCF7 (transcription factor 7)
Diseases named in the same sentence as TCF7 in open-access papers (continued):
Sharing a sentence is not in itself a finding about the gene and the disease.
prostate carcinoma (6 papers, 2014 to 2025). A carcinoma that arises from epithelial cells of the prostate gland. "TCF7 was found to be expressed at high levels and associated with Ras signaling in prostate cancer." (PMID 25436980, 2015). "TCF7 is involved in prostate cancer, and it is highly expressed in immune cells in atherosclerosis plaques." (PMID 36389068, 2022). "We found that inhibiting miR-34a in PC3 as well as the Ras signaling-activated prostate cancer cell line, RasB1, was accompanied by an increase in TCF7, indicating that TCF7 is a candidate target gene for miR-34a." (PMID 25436980, 2015). "In samples of prostate cancer patients, miR-34a levels are inversely correlated with TCF7 expression and a WNT dependent gene signature." (PMID 25436980, 2015). "To examine the inverse correlation between miR-34a and TCF7 expression in prostate cancer progression, we analyzed the correlation of miR-34a and TCF7 in primary and metastatic prostate cancer samples." (PMID 25436980, 2015). "Taken together, these data suggest that TCF7 is an important miR-34a target that augments invasiveness in Ras-activated prostate cancer cells." (PMID 25436980, 2015). "We found that two bone metastatic prostate cancer cell lines (PC3 and a RasG37-mutated RasB1 cell line) have induced TCF7 and Ras signaling-related genes expression." (PMID 25436980, 2015). "We explored the relevance of this finding to study the activation of the TCF7 gene in a public human prostate cancer dataset." (PMID 25436980, 2015). "Taken together, it appears that miR-34a regulates WNT signaling and acts as a tumor suppressor by down-regulating TCF7 to prevent the progression of prostate cancer." (PMID 25436980, 2015). "In this paper, our results highlight the importance of the Ras and WNT cascades during prostate cancer progression, characterized by a miR-down-regulated canonical WNT signaling gene, TCF7, in androgen-independent prostate cancer cells." (PMID 25436980, 2015). "Interestingly, miR-1 was found to suppress vertebrate oncogenic factor, TCF7 of the cWnt/β-catenin pathway during prostate cancer." (PMID 38721525, 2024). "In addition, our clinical data showed that miR-34a expression is significantly higher in prostate cancer patients with a low TCF7 expression, and significantly lower in tumors expressing a high nuclear level of TCF7." (PMID 25436980, 2015). "In addition to that, we observed a correlation between Ras activation, BIRC5, and TCF7 expression in prostate cancer samples." (PMID 25436980, 2015). "Our data show that the bone metastasis and anti-apoptotic effects found in Ras signaling-activated prostate cancer cells require miR-34a deficiency, which in turn aids in cell survival by activating the WNT and anti-apoptotic signaling pathways thereby inducing TCF7 and BIRC5 expressions." (PMID 25436980, 2015). "TFBS analysis of this neomer using FIMO71 and JASPAR72 found that it leads to a gain of a TCF7/TCFL1 motif (MA0769.2), which is known to play a role in prostate cancer malignancy." (PMID 40841759, 2025). "Our pathway analysis further supports the roles these three molecules play in carcinogenesis by mapping the interaction among hsa-miR185-5p, TCF7, and HSP90AA1 to prostate cancer through the PI3K signaling pathway." (PMID 25313363, 2014). "This indicats that tissues from non-tumor prostate tissues, primary and metastatic stage prostate cancer tissues dataset, with down-regulated KRAS signatures, have more TCF7 and BIRC5 expression." (PMID 25436980, 2015).
breast tumor (5 papers, 2017 to 2024). "Later, plant miR159 was identified in human bodies and recognized for its potential to inhibit breast tumor cell growth by targeting the transcription factor 7 (TCF7)." (PMID 39741676, 2024). "They further showed that oral administration of a MIR159 mimicked significantly suppressed the growth of xenograft breast tumors in mice by targeting TCF7." (PMID 28694875, 2017). "TCF7 also participates inchemokine signaling in several cancer types (Zhanget al., 2020), highlighting the relevance of this transcription factor inthe immune microenvironment and immune signaling of breast tumors." (PMID 38100720, 2023).
leukemia (5 papers, 2014 to 2023). A malignant (clonal) hematologic disorder, involving hematopoietic stem cells and characterized by the presence of primitive or atypical myeloid or lymphoid cells in the bone marrow and the blood. "Tcf7-/- leukemias have activated NOTCH signaling and inhibiting this pathway with GSI at least partially impacts their viability." (PMID 35514954, 2022). "Tcf7-/- leukemias are heterogeneous; phenotypically resembling DN3, DN4, and DP thymocytes." (PMID 35514954, 2022). "Further, Tcf7-/- leukemias highly express ID2 and LEF1, particularly in a subset of T cell progenitors with a gene signature predictive of high leukemic potential, suggesting that that suppression of E protein activity may be a feature of transformation in this model." (PMID 35514954, 2022). "BETi synergized with anti-PD1 in vivo, resulting in the reduction of circulating leukemia cells, enrichment of CD8+ T cells in the bone marrow, and increase in expression of Tcf7, Slamf6, and Cxcr5 in CD8+ T cells." (PMID 36681742, 2023). "Like Tcf7-/- leukemias, E2a-/- leukemias have high expression of Lef1 and LEF1 is required for the survival and proliferation of these leukemias." (PMID 35514954, 2022). "PRDM1 knockout promoted TCF7-dependent CAR T cell stemness and proliferation, resulting in marginally enhanced leukemia control in mice." (PMID 36350986, 2022).
ovarian carcinoma (5 papers, 2022 to 2024). A malignant neoplasm originating from the surface ovarian epithelium. "Downregulation of GPR4 leads to a downregulation of TCF7, inhibiting cell growth and cell invasion, and promoting apoptosis of ovarian cancer cells." (PMID 36902589, 2023). "In ovarian cancer ascites, the memory T cells serve as an important supplementary pool of terminal T cells in primary tumors and metastases, suggesting the involvement of TCF7+ Tpm cells in metastatic liver tumors." (PMID 38414027, 2024). "Moreover, lncRNA TCF7 promoted the stemness of ovarian cancer cells via acceleration of spheres formation by promotion of CD44 and CD133 expression." (PMID 36105363, 2022). "Furthermore, lncRNA TCF7 accelerated cisplatin resistance in epithelial ovarian cancer cells." (PMID 36105363, 2022). "LncRNA TCF7 has been found to enhance cell viability, migration, invasion via modulation of ITGB8 in epithelial ovarian cancer." (PMID 36105363, 2022). "Molecular experimental data showed that lncRNA TCF7 promoted the expression of ITGB8 and exerted its oncogenic function in ovarian cancer." (PMID 36105363, 2022).
Type 1 Diabetes (5 papers, 2007 to 2024). "TCF7 plays a role in beta cell function, activates immune system genes, and genetic variants in this gene are associated with Type 1 Diabetes." (PMID 38574408, 2024). "A polymorphism (Pro227Thr;MAFCEU = 0.12) in the TCF7 gene has previously been described to be associated with type 1 diabetes and is predicted to be structurally destabilising." (PMID 17708757, 2007). "We genotyped one TCF7 SNP (C883A; rs5742913), which had previously been associated with type 1 diabetes." (PMID 18045485, 2007). "We found GWAS links between 7 T2D-DMP genes and T2D or related phenotypes, including SPRED2 (T2D), ITPR1 and PLD6 (Diabetic complications), SLC16A3 (BMI), TCF7 (Type 1 Diabetes), RGL3 (blood pressure) and TNIP1 (autoimmune traits)." (PMID 38574408, 2024). "We found some evidence of associations between type 1 diabetes and TAF5L, PDCD1, TCF7 and IL6 (ORs = 1.05 – 1.13; P = 0.0291 – 4.16 × 10-4)." (PMID 18045485, 2007). "Although TAF5L (C744A; rs3753886), PDCD1 (7146G>A; rs11568821), TCF7 (C883A; rs5742913) and IL6 (IL6-174G>C; rs1800795) have previously been associated with type 1 diabetes, the possibility remains that these associations are false positives." (PMID 18045485, 2007). "Consequently, additional studies will be required to ascertain the contribution of TAF5L, PDCD1, TCF7 and IL6 to type 1 diabetes susceptibility." (PMID 18045485, 2007). "TAF5L, PDCD1, TCF7, IL6 and ICAM1 may be amongst the numerous loci with small effects in type 1 diabetes." (PMID 18045485, 2007).
asthma (4 papers, 2015 to 2025). "TCF7 resides on human chromosome 5q31.1, where was proposed as a candidate loci associated with asthma and allergy through genome-wide screens." (PMID 26289446, 2015). "Thus TCF7 could be a potential therapeutic target for asthma, COPD and other lung diseases associated with high-expression of IL-17 through inhibiting IL-17 expression." (PMID 26289446, 2015). "TCF7, a transcription factor, is involved in pulmonary infection, allergy, or asthma through promoting T cells differentiating to Th2 or memory T cells." (PMID 36147486, 2022). "LncRNA TCF7 was found to be contributed to the growth and migration of ASMCs in asthma through targeting TIMMDC1/Akt axis." (PMID 32929606, 2020). "TCF7 is involved in pulmonary infection, allergy or asthma through promoting T cells differentiating to Th2 or memory T cells." (PMID 26289446, 2015). "TCF7 is suggested to be involved in immune responses to pathogens, autoimmune diseases, pulmonary infection, allergy, or asthma through promoting Th2 response, or the formation of memory CD8+ T cells." (PMID 26289446, 2015). "Both Th2 cells and ILC2 cells promoted by TCF7 were found to be involved in asthma." (PMID 26289446, 2015). "ILC2 induced by TCF7 also contributes to Th2 response, and is closely related to asthma." (PMID 26289446, 2015). "Therefore, inhibition of TCF7 in the airway may play a protective role in allergic asthma, and might be considered as a promising target for the future treatment of asthma." (PMID 26289446, 2015).
hepatocellular carcinoma (4 papers, 2016 to 2020). A malignant tumor that arises from hepatocytes. "lncTCF7 recruits the SWI/SNF complex to bind to TCF7 promoter and activate TCF7 expression, and TCF7 activates Wnt pathway to expand hepatocellular carcinoma stem cells." (PMID 26349457, 2016). "For example, in hepatoma cells, transcription of the T-cell factor 7 (TCF7) gene is facilitated by lncRNA TCF7 via the recruitment of SWI/SNF complexes with the lncRNA TCF7 promoter." (PMID 32010629, 2019). "For instance, induction of lncRNA highly up-regulated in liver cancer (HULC), TCF7, and Zinc finger antisense 1 (ZFAS1) could promote tumorigenesis and metastasis of hepatocellular carcinoma (HCC)." (PMID 27589728, 2016).
adenoma (3 papers, 2021). A neoplasm arising from the epithelium. "Perhaps, because of functional redundancy between members of Tcf/Lef family, we detected compensatory increase in Tcf7 or Tcf7l2 transcripts in the Lef1 deleted adenoma cells." (PMID 34788095, 2021). "In normal tissues, low-grade adenomas and high-grade adenomas, the expression level of TCF7 gradually increased." (PMID 34172072, 2021). "However, overexpression of RAC1B did not increase the number of proliferative cells in the normal small intestine nor in the early adenomas and did not increase the expression of canonical Wnt target genes such as Axin2, Tcf7, Lef1 or Ctnnb1." (PMID 34564693, 2021).
Allergy (3 papers, 2015 to 2025). An allergy is an immune response or reaction to substances that are usually not harmful. "Furthermore, in IgE-mediated cow’s milk allergy, we observed that genes such as TCF7, EVL, and BCL11B could be associated with allergy remission and tolerant responses, making them potential candidates as biomarkers for CMA and its prognosis regarding recovery." (PMID 41394805, 2025).
atherosclerosis (3 papers, 2017 to 2023). A disease characterized by the build-up of fatty material and calcium deposition in the arterial wall resulting in partial or complete occlusion of the arterial lumen. "TCF7 was previously found to be highly expressed in both mouse and human subjects with atherosclerosis, induced via the proinflammatory NFκB/AKT pathway." (PMID 37828989, 2023). "We identify two novel genes TCF7 and XCL1 derived from public single-cell-sequencing database of patients with atherosclerosis." (PMID 35792753, 2022). "Studies on the role of TCF7 and XCL1 genes in atherosclerosis have not been widely reported, but these genes are highly expressed in immune cells of patients and mice with atherosclerosis, which may become potential therapeutic targets." (PMID 35792753, 2022).
Autoimmunity (3 papers, 2021 to 2025). The occurrence of an immune reaction against the organism's own cells or tissues. "TCF7 acts with LEF1 to control the maintenance and functional specification of Treg subsets to prevent autoimmunity." (PMID 36077273, 2022).
basal cell carcinoma (3 papers, 2020 to 2021). A carcinoma involving the basal cells. "This study reported the appearance of novel expanded T cell clones, with an activated and exhausted phenotype and enhanced TCF7 expression following anti-PD-1 treatment for metastatic basal cell carcinoma." (PMID 34715028, 2021).
cardiac hypertrophy (3 papers, 2021 to 2023). "Therefore, we hypothesized that lncRNAA02Rik sponged miR-135a and weakened TCF7 suppression, leading to excessive Wnt pathway activity, ultimately causing cardiac hypertrophy." (PMID 34876564, 2021). "TCF7 has been reported to be involved in cardiovascular diseases, such as cardiac hypertrophy and acute coronary syndrome." (PMID 36988257, 2023). "A recent study reported that TCF7 expression was elevated in mouse heart tissue after TAC and in cardiomyocytes treated with Ang-II, and inhibition of TCF7 suppressed the occurrence of cardiac hypertrophy." (PMID 36224570, 2022). "Emerging evidence has shown that TCF7 is involved in tumorigenesis and development, sepsis-induced renal injury, heart development, and cardiac hypertrophy." (PMID 36224570, 2022). "Overall, these data indicated that miR-135a suppressed cardiac hypertrophy by directly binding to TCF7." (PMID 34876564, 2021). "Collectively, these results confirmed that lncRNAA02Rik promoted cardiac hypertrophy via the miR-135a/TCF7 pathway." (PMID 34876564, 2021). "Taken together, our study demonstrated that lncRNAA02Rik contributed to cardiac hypertrophy via sponging miR-135a and activating TCF7, a component of the Wnt signaling pathway." (PMID 34876564, 2021). "Moreover, miR-135a was a direct target for lncRNAA02Rik, and it inhibited cardiac hypertrophy by suppressing TCF7-mediated Wnt pathway activity." (PMID 34876564, 2021). "However, TCF7, an important member of the Wnt signaling pathway, has an ambiguous relationship with cardiac hypertrophy." (PMID 34876564, 2021). "Altogether, our study demonstrated that lncRNAA02Rik upregulation could promote cardiac hypertrophy development via modulating miR-135a expression levels and TCF7 activity." (PMID 34876564, 2021). "Furthermore, forcing miR-135a overexpression exerted a significant protective effect against cardiac hypertrophy by inhibiting the activity of its downstream target TCF7, a critical member of Wnt signaling, and the protective effect could be reversed by AMO-135a." (PMID 34876564, 2021).
Obesity (3 papers, 2022). Accumulation of substantial excess body fat. "Moreover, additional immune checkpoints, such as TIM-3, LAG-3, TIGIT, and EB4, and exhaustion markers, such as TOX, TCF-7, and Eomes, were not increased on CD8 T cells in obesity, suggesting that obesity does not accelerate classical T cell exhaustion." (PMID 35103755, 2022).
thyroid cancer (3 papers, 2014 to 2025). "However, studies have also shown that METTL3 can induce the m6A mRNA modification of TCF1, a downstream effector of the classical Wnt pathway encoded by TCF7, by activating the Wnt pathway, thereby accelerating the progression of thyroid cancer." (PMID 34136491, 2021). "Thus, under low-dose radiation, changes in the abundance of miR-17-5p and miR-20b-5p may influence the cell cycle via interaction with their target gene TCF7 and modulate the development of thyroid cancer." (PMID 25313363, 2014).
allergic asthma (2 papers, 2015 to 2025). A asthma with a basis in a pathological type I hypersensitivity reaction. "An experimental model of allergic asthma induced by ovalbumin in mice showed TCF7 was required in the production of the Th2 cytokine, IL-4." (PMID 26289446, 2015). "In addition, TCF7 promotes T-cell differentiation to Th2 or memory T cells, consistent with allergic asthma being the result of immune system dysregulation." (PMID 40504147, 2025).
cervical cancer (2 papers, 2023 to 2025). A primary or metastatic malignant neoplasm involving the cervix. "In a word, Mg-Ca-nHAC composite scaffolds exerted anti-tumor effects by activating the Wnt/β-catenin/TCF7 signaling pathway to inhibit EMT in cervical cancer." (PMID 41367628, 2025). "For example, TCF7 promotes the invasion of cervical cancer cells by sponging miR-155-5p, which is reversed by TCF7 downregulation." (PMID 37190145, 2023). "The data from both groups collectively indicated that LGK974 and Mg-Ca-nHAC could inhibit cervical cancer cells by inhibiting the Wnt/β-catenin/TCF7 pathway and regulating the expression of EMT markers." (PMID 41367628, 2025).
glioblastoma (2 papers, 2023 to 2024). The most malignant astrocytic tumor (WHO grade IV). "To validate the role of lncTCF7 in regulating TCF7 expression, we stably knocked down lncTCF7 in the U251 glioblastoma cell line using two shRNA plasmids." (PMID 39169000, 2024). "Together, our results show that SND1 interacts with the SWI/SNF complex and that the SWI/SNF complex localizes to the TCF7 promoter in glioblastoma cells." (PMID 39169000, 2024). "This work validates the role of lncTCF7 in recruiting the SWI/SNF complex to the TCF7 promoter in glioblastoma cells." (PMID 39169000, 2024). "This work demonstrates for the first time that FOXO1 promotes the expression of WNT pathway target genes LEF1 and TCF7 in basal‐like breast and glioblastoma multiforme cells." (PMID 37584250, 2023).
immune deficiency (2 papers, 2014 to 2018). "Recently TCF-7 has been shown to induce Th2 and Th17 inflammation, supporting the hypothesis that dysfunction of this pathway at any stage of T cell differentiation could lead to immune deficiency." (PMID 25329529, 2014).
influenza (2 papers, 2019 to 2025). An acute viral infection of the respiratory tract, occurring in isolated cases, in epidemics, or in pandemics; it is caused by serologically different strains of viruses (influenzaviruses) designated A, B, and C, has a 3-day incubation period, and usually lasts for 3 to 10 days. "Individuals with SAS‐1high‐MAS‐1low status prior to influenza or SARS‐CoV‐2 vaccination maintained lower pathogenic triad burdens, higher TCF7 levels, and elevated expression of gene signature modules linked to lymphocyte subsets (e.g., plasma cells) associated with superior vaccine responsiveness." (PMID 40264357, 2025). "Published transcriptional profiles of NK cells, ILC1, and influenza-specific Id2-deficient mouse CD8+ T cells showed a striking concordance of Id2-dependent expression with our innateness gradient genes, highlighted by TBX21, ZEB2, IL18RAP, CCR7, TCF7, cytotoxicity, and KLR genes." (PMID 30737409, 2019).
malaria (2 papers, 2025). Malaria is a serious and sometimes fatal disease caused by a parasite that commonly infects a certain type of mosquito which feeds on humans. "We, therefore, examined the signature genes associated with cluster 10 and found enrichment of the transcription factor TCF1 (gene name Tcf7); this has been associated with circulating TFH cells in a mouse model of malaria, but we found no significant enrichment for PD1, CXCR5, or BCL6." (PMID 40214640, 2025).